RN7SL393P (RNA, 7SL, cytoplasmic 393, pseudogene)
Gene: Miscellaneous RNA gene on chromosome 2 (158,447,166 to 158,447,461, reverse strand). Ensembl gene ENSG00000243723.
Homologues: Orthologues: chimpanzee Metazoa_SRP (97% identical), macaque Metazoa_SRP (90% identical), rat Metazoa_SRP (64% identical). Paralogues in human: RN7SL3 (80% identical), RN7SL1 (79% identical), RN7SL2 (78% identical), RN7SL655P (77% identical), RN7SL679P (77% identical), RN7SL230P (77% identical), RN7SL448P (77% identical), RN7SL20P (76% identical), RN7SL220P (76% identical), RN7SL357P (76% identical), RN7SL630P (76% identical), RN7SL664P (76% identical), and 704 more.